SLC30A8 (solute carrier family 30 member 8)
Diseases named in the same sentence as SLC30A8 in open-access papers (continued):
Sharing a sentence is not in itself a finding about the gene and the disease.
type 2 diabetes (continued). "Han X., Luo Y., Ren Q., Zhang X., Wang F., Sun X., Zhou X., Ji L.Implication of genetic variants near SLC30A8, HHEX, CDKAL1,CDKN2A/B, IGF2BP2, FTO, TCF2, KCNQ1, and WFS1 in type 2diabetes in a Chinese population." (PMID 35434484, 2022). "Genetically informed drug design has been estimated to double the success rate of clinical drug development, for example the development of SLC30A8 antagonists as a potential therapy for type 2 diabetes." (PMID 33465068, 2021). "Variants in several genes show strong association with type 2 diabetes risk, including those in TCF7L2, SLC30A8 and MTNR1B." (PMID 31161346, 2019). "A previous functional study of SLC30A8 suggested that reduced zinc transport increases type 2 diabetes risk." (PMID 29777116, 2018). "This study examined the association of the polymorphic markers of the genes KCNJ11, SLC30A8, CDKAL1, CDKN2B and FTO with type 2 diabetes mellitus in Russia." (PMID 28717589, 2017). "We confirmed the associations of genetic variations in SLC30A8, CDKN2A/CDKN2B, KCNQ1, CENTD2 with type 2 diabetes." (PMID 25587982, 2015). "In the GLACIER cohort, eleven loci (including the known type 2 diabetes genes TCF7L2 and SLC30A8) were nominally associated with IFG cross-sectionally, and MTNR1B and G6PC2 were also associated with development of IFG in longitudinal analyses." (PMID 22984506, 2012). "We showed SNPs from seven loci, including GIPR, TCF7L2, MADD, CRY2, GLIS3, PROX1 and SLC30A8, had an effect on type 2 diabetes in our samples." (PMID 21103350, 2010). "The current study confirmed the association between PPARG, KCNJ11, CDKAL1, CDKN2A-CDKN2B, IDE-KIF11-HHEX, IGF2BP2 and SLC30A8 and type 2 diabetes." (PMID 19862325, 2009). "In this study, we confirmed the effects of variations in PPARG, KCNJ11, CDKAL1, CDKN2A-CDKN2B, IDE-KIF11-HHEX, IGF2BP2 and SLC30A8 on type 2 diabetes." (PMID 19862325, 2009). "We recently reported that type 2 diabetes risk alleles in TCF7L2, CDKAL1, and SLC30A8 impair proinsulin-to-insulin conversion." (PMID 19088850, 2008). "In vitro structure–function studies have proposed mechanisms by which SLC30A8 LoF directly affects zinc-mediated insulin storage, processing and secretion, suggesting a possible path to type 2 diabetes treatment that is independent of weight loss." (PMID 41020949, 2025). "Our data suggest that complete loss of SLC30A8 Function is safe and even well tolerated in humans, but is not completely protective against type 2 diabetes." (PMID 41020949, 2025). "Moreover, investigations into common genetic variants linked to type 2 diabetes, such as TCF7L2, SLC30A8, and CDKAL1, underscore the interconnectedness of GDM and metabolic disorders." (PMID 38694942, 2024). "Interestingly, at least 12 genes including SLC2A2, G6PC2, SLC30A8, PCSK1 and RAPGEF4, also overlap with previously implicated genes from genome wide association studies (GWAS) for type 2 diabetes mellitus and blood glucose loci." (PMID 31682591, 2020). "Our results from the blood glucose analysis validated well-established gene loci associated with type 2 diabetes with common SNPs in CDKAL1, SLC30A8, SND1-PAX4, IDE-KIF11-HHEX, CDKN2A-CDKN2B, KCNQ1 and CDC123,33,37,38 and identified a novel locus associated with FBG in DENND5B." (PMID 32355288, 2020). "Hypoxia might therefore contribute to the downregulation of Slc30a8 previously observed in human type 2 diabetes islets." (PMID 24865615, 2014). "A majority of genes associated with type 2 diabetes from this meta-analysis (ADCY5, CDKAL1, CDKN2A/B, HHEX, IGF2BP2, SLC30A8, TCF7L2 and KCNQ1) are involved in pancreatic beta cell function, while two are implicated in insulin sensitivity (PPARG) and adiposity (FTO)." (PMID 25145545, 2014). "Recent genome wide association studies have found the islet-restricted Zinc transporter ZnT8 (SLC30A8) as a potential controller of insulin secretion and hence may modulate the risks of developing type 2 diabetes." (PMID 22515411, 2012).
type 2 diabetes (continued). "Our results suggest that SLC30A8 might therefore have a role in expansion of the β-cell and benefit from PPARγ agonists in the treatment of type 2 diabetes." (PMID 22208362, 2011). "Most of the genes associated with type 2 diabetes (TCF7L2, SLC30A8, HHEX, CDKAL1, CDKN2A/B and IGF2BP2) might be implicated in beta cell function." (PMID 20161779, 2010). "However, after correction of multiple comparisons, only the association between SNPs from CDKAL1, CDKN2A-CDKN2B, IDE-KIF11-HHEX, IGF2BP2 and SLC30A8 and type 2 diabetes remained to be significant." (PMID 19862325, 2009). "Furthermore, type II diabetes was associated with SLC16A11, SLC30A8, SLC39A11 and MTCH2." (PMID 40355757, 2025). "The third most negative was found in SLC30A8 and is associated with Type 2 diabetes." (PMID 28774272, 2017). "Several studies have shown the association of solute carrier family 30 (zinc transporter) member 8 (SLC30A8) rs13266634 with type 2 diabetes (T2D)." (PMID 24393180, 2014). "However, in 2007, several reproducible genome-wide association studies (GWASs) confirmed these well-established susceptibility genes and identified a number of new loci (SLC30A8, HHEX, CDKN2A/B, IGF2BP2, GCKR, FTO, and CDKAL1) at which common variants influence risk of type 2 diabetes in Europeans." (PMID 20161779, 2010). "Compared with all cell types, beta cells had the most genes with time–glucose interaction effects, featuring several well-established type 2 diabetes genes, including INS, ABCC8, SLC30A8 and PCBD1." (PMID 38967666, 2024). "We identify many genes with a well-defined role in relationship to type 2 diabetes (e.g., ABCC8, SLC30A8), including 18 of the 132 type 2 diabetes effector genes from the Type 2 Diabetes Knowledge Portal." (PMID 37333221, 2023). "Module 84 contained three effector genes from the Type 2 Diabetes Knowledge Portal—ABCC8, SLC30A8, and G6PC2—and module 103 included two effector genes: PAX6 and STARD10." (PMID 37333221, 2023). "It is interesting that type 2 diabetes genes (e.g., KCNQ1 and SLC30A8) showed limited impacts on fasting glucose in the normoglycemic populations, although they also impaired insulin secretion." (PMID 20668700, 2010). "Very recently, genetic variations within four novel genetic loci (SLC30A8, HHEX, EXT2, and LOC387761) were reported to be more frequent in subjects with type 2 diabetes than in healthy controls." (PMID 17786204, 2007). "Of the 132 type 2 diabetes Knowledge Portal effector genes, we identified 18 (14%) as candidate effector genes for at least one phenotype, including ABCC8, KCNJ11, NKX2–2, G6PC2, PAM, HNF4A, SLC30A8, RFX6, PCSK1, and GLIS3." (PMID 37333221, 2023). "In another study, allele-specific expression of several genes in islets (ANPEP, CAMK2B, HMG20A, KCNJ11, NOTCH2, SLC30A8 and WFS1) showed that even subtle changes of gene dosage may have significant consequences for development of type 2 diabetes." (PMID 30497374, 2018). "The association of type 2 diabetes mellitus (T2DM) with the KCNJ11, CDKAL1, SLC30A8, CDKN2B, and FTO genes in the Russian population has not been well studied." (PMID 28717589, 2017). "Besides, the effects of previous reported type 2 diabetes and/or fasting glucose loci G6PC2, GCK, GCKR, MTNR1B, DGKB, SLC30A8 and TCF7L2 were also replicated in the meta-analysis." (PMID 21103350, 2010). "Similarly, transcripts of candidate genes for type 2 diabetes (Blk, C2cd4a, C2cd4b, Cdkn2a, Hnf1a, Mtnr1b, Pou5f1, Slc30a8) and type 1 diabetes (Cd69, Il2, IL27) were not expressed in the brain." (PMID 39920851, 2025). "We also identified two SLC30A8 knockouts with type 2 diabetes, indicating that protection from disease is not absolute, probably due to strong environmental factors such as diet or other polygenic risk factors that could not be evaluated in this study." (PMID 41020949, 2025).
type 2 diabetes (continued). "Recently, several genome-wide and candidate gene association studies have identified many novel genetic loci for type 2 diabetes (T2D); among these genes, CDKAL1, IGF2BP2, SLC30A8, CDKN2A/B, HHEX, FTO, TCF2, KCNQ1, and WFS1 are the most important." (PMID 20509872, 2010). "Importantly, SLC30A8 LoF did not impact BMI, and may represent an alternative mechanism for type 2 diabetes treatment and prevention that is independent of currently available weight loss therapies." (PMID 41020949, 2025).
diabetes (52 papers, 2008 to 2025). "The study also revealed regionally enriched variants with clinically important impacts including CYP2C19 (drug metabolism), HBB (thalassemia risk), and SLC30A8 (diabetes susceptibility)." (PMID 40898550, 2025). "After adjusted multivariate analysis, only SLC30A8 and diabetes remained independently associated with an increased risk of android obesity (OR = 2.50; p = 0.003 and OR = 3.63; p = 0.004, respectively)." (PMID 41009965, 2025). "In this large genome-wide GxE interaction analysis involving more than 30,000 colorectal cancer cases, we found that the association of diabetes status with colorectal cancer was modified by common genetic variants located within the SLC30A8 and LRCH1 genes." (PMID 37365285, 2023). "We found that the association of diabetes with colorectal cancer risk was modified by variants located in the SLC30A8 gene." (PMID 37365285, 2023). "In our primary analysis we found that the association between diabetes and colorectal cancer risk was modified by variants on chromosome 8q24.11 within the SLC30A8 gene based on the 3-d.f." (PMID 37365285, 2023). "Dietary habits influence the association of six genes (C2CD4B, CDKN2B, GIPR, HHEX, SLC2A2, and SLC30A8) forming the third cluster with diabetes, adipogenesis, and cardiovascular risk." (PMID 36982283, 2023). "Our top hit, rs3802177 in the SLC30A8 gene is in LD (R2 = 1) with rs13266634, which was associated with diabetes risk in a previous GWAS (as well as in our analysis) and has also been shown to modify insulin secretion." (PMID 37365285, 2023). "Five independent studies examined the association between SNPs for the SLC30A8 gene, Zn intake, the risk of T2D diabetes, and glucose metabolism biomarkers." (PMID 28218639, 2017). "The findings reported herein that the diabetes risk genotype C/C at SNP rs13266634 of the SLC30A8 gene encoding the β-cell Zn transporter ZnT8 is associated with a higher total islet Zn concentration, is potentially of clinical significance." (PMID 28352089, 2017). "In addition, recent concerted studies have revealed that the rare LOF variants of SLC30A8 protect against diabetes in human subjects." (PMID 35842441, 2022). "In addition, a mutation in solute carrier family 30 member 8 (SLC30A8), which encodes an islet zinc transporter, decreases the risk of diabetes by 65% even in the presence of risk factors such as obesity." (PMID 32270227, 2020). "The breakthrough discovery that the common polymorphism in zinc transporter SLC30A8/ZnT8 may increase susceptibility to type 2 diabetes provided novel insights into the role of zinc in diabetes." (PMID 29415457, 2018). "It should be mentioned here that rat Tcf7l2, and the exclusively pancreatic islet expressed Slc30a8, whose variants confer both diabetes risk and protective effects and whose autoantibodies are detected in T1D patients, have targeted mutations introduced via zinc finger nuclease (ZFN) mutagenesis." (PMID 27602200, 2016). "The dependence on ZnT8 of hypoxia-induced changes in cell survival may contribute to the actions of SLC30A8 variants on diabetes risk in humans." (PMID 24865615, 2014). "STZ treatment also suppressed expression of a wide range of genes linked with key β-cell functions or diabetes development, such as G6pc2, Slc2a2 (Glut2), Slc30a8, Neurod1, Ucn3, Gad1, Isl1, Foxa2, Vdr, Pdx1, Fkbp1b and Abcc8, suggesting global β-cell defects in STZ-treated islets." (PMID 23828045, 2013). "Although little is known about the mechanism through which the rs13266634 polymorphism in the SLC30A8 gene confers susceptibility to diabetes, we speculate that reduced endogenous expression of the ZnT8 transporter constitutes one possible mechanism." (PMID 19479076, 2009). "However, data from the German prospective cohort studies BABYDIAB and BABYDIET suggested that SLC30A8 may influence age at onset of diabetes and rate of progression within predisposed individuals, perhaps by its effect on insulin production." (PMID 31444530, 2019).
diabetes (continued). "Indeed, a recent study found that rare loss-of-function variants in SLC30A8 are protective against diabetes, which may propose that the rs13266634 C-allele could have some kind of gain-of-function effect." (PMID 29093761, 2017). "The present data, in conjunction with the prior population-based studies suggesting a role for the diabetes-associated SLC30A8 polymorphism in insulin secretion or action, raise the question of whether SLC30A8 risk alleles directly impact ZnT8 expression level in vivo." (PMID 19479076, 2009). "“Tier 2” additionally includes four genes within the top 50 genes and either being causal for monogenic diabetes or harboring causal coding variants of T2D35 (GCK, SLC30A8, ABCC8, and PAM)." (PMID 37292813, 2023). "In a study of diabetic mice, SLC30A8 gene expression levels were inhibited in the pancreas of animals with this pathology, indicating that it is related to diabetes." (PMID 37324267, 2023). "Promoter methylation is generally associated with gene silencing, and this potential regulation of SLC30A8 expression and its connection to diabetes should continue to be studied." (PMID 35745255, 2022). "We also found association between CDKN2A/2B (rs10811661), SLC30A8 (rs13266634), and TCF7L2 (rs7903146) and diabetes-related quantitative traits." (PMID 29871606, 2018). "While associations at the GCK, SLC30A8 and G6PC2 loci confirm or extend previous work done on the genetic basis of diabetes or fasting glucose, our replicated findings at HK1 are novel." (PMID 19096518, 2008). "Although eQTL or cASE analyses in human islets did not support the association between these additional genes and diabetes risk, the transcriptional regulator JQ1 lowered the expression of multiple genes at the SLC30A8 locus and enhanced stimulated insulin secretion." (PMID 37502937, 2023). "These earlier reports indicate that SLC30A8 may influence cell viability under stressed conditions which pertain in diabetes." (PMID 37502937, 2023). "This is of interest as the SLC30A8 genotype may be important to consider as a factor that contributes to progression to clinical onset of diabetes." (PMID 34983671, 2022). "We examined whether the other two significant genes in the study, SLC30A8 and MC4R, associated with diabetes traits in our analysis." (PMID 34732801, 2021). "Of particular relevance to diabetes is the most well studied zinc transporter ZnT8 (SLC30A8)." (PMID 25797421, 2015). "It will also be important to analyse both newly diagnosed T1D patients 29 as well as children at risk such as in, for example, the TEDDY (The Environmental Determinants of Diabetes in the Young) study 34, to relate specificity and affinity to the SLC30A8 genotype." (PMID 25178386, 2015). "We aimed to characterise the possible longitudinal associations of common diabetes-susceptibility variants in the KCNJ11, PPARG, TCF7L2, IGF2BP2, CDKAL1, SLC30A8 and HHEX gene loci, with fasting glucose level; and of an obesity-associated variant in the FTO gene, with body mass index (BMI)." (PMID 20929593, 2010). "While genetic variants of GCK and G6PC2 are known to influence fasting glucose concentrations in non-diabetics, the association with the diabetes gene SLC30A8 has not been previously identified." (PMID 19096518, 2008). "Thus, rs13266634 has been thought to be related to diabetes risk, as it affects the expression of SLC30A8, and negative regulation of ZnT8 is considered to disrupt the stability of insulin molecules." (PMID 37324267, 2023). "It has been recently shown that zinc supplementation appears to differently affect the early insulin response to glucose, according to rs13266634 genotype, and could be beneficial for diabetes prevention and/or treatment for some individuals based on SLC30A8 variation." (PMID 26559814, 2015).
diabetes (continued). "In the multivariate logistic regression analysis, the following variables were included: SLC30A8 (CC), PSRC1 (AA + GA), KIF6 (CC), diabetes, age, smoking, hypertension, dyslipidaemia, BMI, and physical inactivity." (PMID 41009965, 2025). "The associations of SLC30A8 and SLC16A11 with diabetes are well-described, but the disease mechanisms have not been fully elucidated yet and accordingly ClinVar and Orphanet do not report this association." (PMID 40355757, 2025). "The most common SLC30A8 variant, rs13266634 is associated with GADA negative diabetes in Malaysian subjects, and this association is more pronounced among Malaysian Indian subjects." (PMID 24393180, 2014). "The aim of this investigation was to study the association of alternative SLC30A8 SNPs (rs7002176, rs1995222) and haplotypes with GADA negative diabetes, and further to replicate the association of the most common variant, rs13266634 in Malaysian subjects." (PMID 24393180, 2014). "While associations with the GCK, SLC30A8, and G6PC2 genes have previously been identified in genetic studies of diabetes and blood glucose concentration, the findings at HK1 are novel." (PMID 19096518, 2008). "In addition, the alternative SLC30A8 variant, rs1995222 is significantly linked with rs13266634 (r2 = 0.2) and shows a mild association with GADA negative diabetes." (PMID 24393180, 2014). "The aim of this study is to assess the association of the alternative SLC30A8 variants, rs7002176 and rs1995222 as well as the most common variant, rs13266634 and haplotypes with glutamic acid decarboxylase antibodies (GADA) negative diabetes in Malaysian subjects." (PMID 24393180, 2014). "The “β-cell-related” gene group includes SLC30A8, SIX3, and PAM, genes involved in pancreatic β-cell function but not monogenic diabetes." (PMID 37292813, 2023). "We are currently conducting a larger study with age and BMI matched Non-DM participants and T2DM participants that do not take diabetes medications that use an insulin infusion protocol of 600 pmol/L and involves an analysis of the genome of SLC30A8." (PMID 29791512, 2018).